COX7B (cytochrome c oxidase subunit 7B)
Description:
Component of the cytochrome c oxidase, the last enzyme in the mitochondrial electron transport chain which drives oxidative phosphorylation. The respiratory chain contains 3 multisubunit complexes succinate dehydrogenase (complex II, CII), ubiquinol-cytochrome c oxidoreductase (cytochrome b-c1 complex, complex III, CIII) and cytochrome c oxidase (complex IV, CIV), that cooperate to transfer electrons derived from NADH and succinate to molecular oxygen, creating an electrochemical gradient over the inner membrane that drives transmembrane transport and the ATP synthase. Cytochrome c oxidase is the component of the respiratory chain that catalyzes the reduction of oxygen to water. Electrons originating from reduced cytochrome c in the intermembrane space (IMS) are transferred via the dinuclear copper A center (CU(A)) of subunit 2 and heme A of subunit 1 to the active site in subunit 1, a binuclear center (BNC) formed by heme A3 and copper B (CU(B)). The BNC reduces molecular oxygen to 2 water molecules using 4 electrons from cytochrome c in the IMS and 4 protons from the mitochondrial matrix (By similarity). Plays a role in proper central nervous system (CNS) development in vertebrates.
Synonyms: APLCC; LSDMCA2
Tractability: Small molecule: a structure with a bound ligand is known. Antibody: UniProt predicts a signal peptide or a membrane-spanning region. PROTAC: ubiquitination databases record sites on it; its protein half-life has been measured.
Gene: Protein-coding gene on chromosome X (77,895,727 to 77,907,376, forward strand). Ensembl gene ENSG00000131174.
Subcellular location: Mitochondrion inner membrane
Pathways (Reactome):
Metabolism: Complex IV assembly; Respiratory electron transport
Cellular responses to stimuli: Cytoprotection by HMOX1
Gene Ontology:
Molecular function: protein binding; cytochrome-c oxidase activity
Biological process: central nervous system development; cellular respiration; mitochondrial electron transport, cytochrome c to oxygen; oxidative phosphorylation; proton transmembrane transport
Cellular component: mitochondrial inner membrane; mitochondrial membrane; mitochondrion; respiratory chain complex IV; membrane
Gene-disease validity (ClinGen):
ClinGen rates the evidence that COX7B causes each of these diseases.
mitochondrial disease (X-linked): Limited.
Homologues: Orthologues: chimpanzee COX7B (99% identical), macaque COX7B (95% identical), tropical clawed frog cox7b (64% identical). Paralogues in human: COX7B2 (70% identical).
Diseases named in the same sentence as COX7B in open-access papers:
COX7B is named in the same sentence as 40 diseases in open-access papers, as found by Europe PMC text mining. Sharing a sentence is not in itself a finding about the gene and the disease. The quoted sentences say what the papers report.
esophageal cancer (4 papers, 2023 to 2025). A primary or metastatic malignant neoplasm involving the esophagus. "Moreover, some CRGs, including PIH1D2, SLC23A2, SLC25A5, ATP7A, PDHX and COX7B, were reported to be tightly linked with the grading and immune infiltration of esophageal carcinoma." (PMID 37380924, 2023). "COX7B is also identified as a novel biomarker for patients with esophageal cancer, and its high expression is significantly related to the poor prognosis of esophageal cancer." (PMID 41364140, 2025). "In the oncological realm, investigations have unveiled a correlation between COX7B expression and infiltrative immune cells in esophageal carcinoma." (PMID 38702721, 2024).
microphthalmia (4 papers, 2013 to 2024). Congenital or developmental anomaly in which the eyeballs are abnormally small. "Previously identified mitochondrial proteins associated with the development of microphthalmia, namely HCCS and COX7B, were shown to induce a reactive oxygen species (ROS)‐dependent induction of caspase 9‐mediated cell death." (PMID 30389680, 2019). "For instance, HCCS and COX7B are the only human MRC-related proteins, the impairment of which causes microphthalmia." (PMID 23239471, 2013). "Interestingly, the four females with a COX7B mutation did not display microphthalmia/anophthalmia, but variable linear skin defects on the neck and face at birth." (PMID 24735900, 2014).
Sepsis (4 papers, 2023 to 2026). Sepsis is defined as life-threatening organ dysfunction caused by a dysregulated host response to infection. "In summation, our findings underscore the important diagnostic and prognostic utility of COX7B in sepsis." (PMID 38702721, 2024). "According to our research, COX7B is closely associated with the diagnosis and prognosis of sepsis." (PMID 38702721, 2024). "Integrating high-throughput sequencing with bioinformatics, this study identified two mitochondrial genes (COX7B, NDUFA4) closely linked with sepsis prognosis." (PMID 38702721, 2024). "Cyclooxygenase 7B (COX7B), one component of complex IV of the mitochondrial electron transport chain, regulating COX7B can significantly enhance mitochondrial performance of immune cells in sepsis." (PMID 39262873, 2024). "The mitochondrial-associated genes (MiAGs) COX7B and NDUFA4 are intimately linked with the prognosis of sepsis, offering potential guidance for research into the mechanisms underlying sepsis." (PMID 38702721, 2024). "Consequently, sepsis-related high transcript levels of COX7B and NDUFA4 were primarily found in immune-related cells, with elevated transcription in monocyte-macrophages, T cells, and B cells." (PMID 38702721, 2024). "Survival analysis demonstrated that patients with lower expression levels of COX7B and NDUFA4 exhibited a higher day survival rate over 28 days, inversely correlating with sepsis mortality." (PMID 38702721, 2024). "Recently, scholars have established an ex vivo sepsis model by inciting RAW264.7 macrophages with LPS, unearthing a heightened expression of COX7B in sepsis and its vital role in mitochondrial quality imbalance amid lipopolysaccharide-treated macrophages." (PMID 38702721, 2024). "Meta-analysis indicated significant overexpression of COX7B and NDUFA4 in the sepsis group in contrast to the normal group (P < 0.01)." (PMID 38702721, 2024). "Furthermore, we identified through single-cell sequencing that the high transcription levels of COX7B and NDUFA4 related to sepsis are mainly found in immune-related cells, with increased transcription in monocyte macrophages, T cells, and B cells." (PMID 38702721, 2024). "Patients with low expression of COX7B and NDUFA4 exhibited higher 28-day survival rates compared to the high-expression group, showing a negative correlation with the survival rate of sepsis patients, with statistically significant differences (P < 0.05)." (PMID 38702721, 2024).
breast carcinoma (3 papers, 2021 to 2023). "Together, these in vitro results supported a cause–effect relationship between Cox7b protein expression and the brain tropism of human metastatic breast cancer cells." (PMID 36139533, 2022). "Cox7b refers to the part of a likely wider family of proteins important for breast cancer brain tropism in mice." (PMID 37273454, 2023).
Parkinson disease (3 papers, 2020 to 2026). A progressive degenerative disorder of the central nervous system characterized by loss of dopamine producing neurons in the substantia nigra and the presence of Lewy bodies in the substantia nigra and locus coeruleus. "Among the proteins involved in the Alzheimer's disease and Parkinson's disease pathways, in addition to the fact that we already know that COX7B, COX6A2 and UQCRQ affect the function of mitochondria, downregulation of CASP9 is thought to lead to neurodegenerative diseases." (PMID 33247215, 2020). "There were three proteins included COX7B, COX6A2, and UQCRQ associated with the following pathways: oxidative phosphorylation (P = 0.003), cardiac muscle contraction (P = 0.047), Alzheimer's disease (P = 0.042), and Parkinson's disease (P = 0.028)." (PMID 33247215, 2020). "In addition, COX7B, NDUFB3, and UQCRQ were both primarily enriched in some pathways, such as ribosome, Huntington disease, oxidative phosphorylation, Alzheimer disease, and Parkinson disease." (PMID 41517693, 2026).
atherosclerosis (2 papers, 2019 to 2020). A disease characterized by the build-up of fatty material and calcium deposition in the arterial wall resulting in partial or complete occlusion of the arterial lumen. "A recent study claimed that the COX7B is a potential novel gene target for FH treatment; however, authors did not provide supportive evidence for metabolic network and pathway links between the Atherosclerosis and FH." (PMID 32760426, 2020).
bladder cancer (2 papers, 2018 to 2022). "Low COX7B levels correlated with higher mortality rates in patients with various types of cancer and were significantly associated with poor response to chemotherapy in urinary bladder cancer." (PMID 30367559, 2018). "A Kaplan‐Meier analysis of the TCGA provisional dataset for bladder cancer revealed a marked difference in mortality for COX7B, showing that low COX7B levels significantly predicted poor prognosis (P = 0.006)." (PMID 30367559, 2018). "Then we examined COX7B by immunohistochemistry in a cohort of 16 bladder cancer samples from patients who underwent neoadjuvant CDDP‐based chemotherapy (NAC) before surgery." (PMID 30367559, 2018). "Notably, the surrogate marker CD63 could distinguish low-COX7B subclones; thus, the authors speculated that COX7B and CD63 together contribute to platinum resistance in platinum-naïve bladder cancer." (PMID 36338973, 2022).
cardiomyopathies (2 papers, 2017 to 2021). "We suggest that individuals with MLS syndrome or variants or cytogenetic abnormalities involving NDUFB11, HCCS, or COX7B should be considered at risk for histiocytoid CM and screening for evidence of malignant arrhythmias and cardiomyopathy may be appropriate." (PMID 28050600, 2017).
Huntington disease (2 papers, 2024 to 2026). Huntington disease (HD) is a rare neurodegenerative disorder of the central nervous system characterized by unwanted choreatic movements, behavioral and psychiatric disturbances and dementia. "In the context of female patient samples and control samples, the crucial gene COX7B, when highly expressed, displayed enrichment in Huntington's disease, while its low expression counterpart was enriched in complement and coagulation." (PMID 38965390, 2024).
microcephaly (1 paper, 2019). A congenital or acquired developmental disorder in which the circumference of the head is smaller than normal for the person's age and sex. "Furthermore, mutations lead to microcephaly, indicating a role for COX7B in brain and eye development." (PMID 30876387, 2019).
nasopharyngeal carcinoma (1 paper, 2022). A carcinoma arising from the nasopharyngeal epithelium. "Consistently, in nasopharyngeal carcinoma (NPC), COX7B was found to hold a high positive rate (84.24%) in tumor samples and was thought to be a putative molecular marker in NPC." (PMID 35995782, 2022).
neurocutaneous disorder (1 paper, 2014). "Additional evidence for implication of mitochondrial dysfunction in MLS syndrome came from the discovery of COX7B as the second gene for this neurocutaneous disorder; it encodes a structural subunit of MRC complex IV." (PMID 24735900, 2014).
psoriasis (1 paper, 2024). An autoimmune condition characterized by red, well-delineated plaques with silvery scales that are usually on the extensor surfaces and scalp. "Using single-cell metabolic analysis, we found that the "winner cells" promote OXPHOS pathway upregulation by COX7B and lead to increased ROS through glucose metabolism, thereby promoting the hyperproliferation of basal cells in psoriasis." (PMID 38855186, 2024). "We further found that COX7B promotes psoriasis development by modulating the activity of the PPAR signaling pathway by bulk RNA-seq analysis." (PMID 38855186, 2024).
triple-negative breast carcinoma (1 paper, 2022). An invasive breast carcinoma which is negative for expression of estrogen receptor (ER), progesterone receptor (PR), and human epidermal growth factor receptor 2 (HER2). "Comparing RNAseq data from wild-type human cancer cells and two independent brain-seeking variants, we identified cyclooxygenase 7b (Cox7b) in Complex IV of the mitochondrial electron transport chain as a driver of triple-negative breast cancer brain metastasis." (PMID 36139533, 2022).
cancer (6 papers, 2018 to 2024). A tumor composed of atypical neoplastic, often pleomorphic cells that invade other tissues. "In this study, the result indicated that several types of cancers had an abnormally high amount of COX7B." (PMID 37273454, 2023). "This is the case of Cox7b, which sensitizes cancers to cisplatin chemotherapy, with high Cox7b expression in primary tumors being a favorable factor for overall patient survival upon cisplatin treatment." (PMID 36139533, 2022). "High Cox7B expression was identified as an independent poor prognosis factor for overall patient survival in all three cancer types." (PMID 36139533, 2022). "Our results offer a new transcriptome landscape of platinum‐resistance that provides valuable insights into chemosensitivity and drug resistance in cancers, and we identify a novel platinum resistance gene, COX7B, and a surrogate marker, CD63." (PMID 30367559, 2018). "Further, we identified the existence of subclone with low‐COX7B that behaved as cancer cells with acquired platinum‐resistance in platinum‐naïve cancers." (PMID 30367559, 2018). "We further identified the association between COX7B and CD63 and observed that 59% of the 32 cancer types in TCGA show a positive correlation with COX7B." (PMID 30367559, 2018). "Third, we demonstrated a low COX7B subclone, behaving as cancer cells with acquired platinum‐resistance in platinum‐naïve cancer." (PMID 30367559, 2018). "Here, mapping the transcriptome of cancers treated with CDDP by scRNA‐seq, we uncovered a novel gene, COX7B, associated with platinum‐resistance, and surrogate marker, CD63." (PMID 30367559, 2018). "Knockdown of COX7B in cancer cells decreased the sensitivity of CDDP whereas overexpression recovered the sensitivity of CDDP." (PMID 30367559, 2018). "Additionally, COX7B, IARS2, COA3 and NDUFA1 were associated with platinum resistance, cancer cell proliferation and invasion, highlighting their significance as potential therapeutic targets and prognostic biomarkers." (PMID 38534098, 2024). "Because the level of COX7B expression varied in accordance with the variety of cancers, we speculated that it may act either as a tumor promotor or a tumor suppressor." (PMID 37273454, 2023). "Analyzing scRNA‐seq data from platinum‐naïve cancer cells demonstrated a low‐COX7B subclone that could be sorted out from bulk cancer cells by assaying CD63." (PMID 30367559, 2018). "Knockdown of COX7B decreased the sensitivity of CDDP in platinum‐naïve cancer cells, and overexpression of COX7B could re‐sensitize the cells to CDDP in platinum‐resistant cancers." (PMID 30367559, 2018). "In sum, the results from both cell line experiments demonstrated that COX7B and CD63 were closely related in cancers." (PMID 30367559, 2018). "Second, we did not give any direct in vivo proof that the COX7B upregulation had any consequences that promoted the development of cancer." (PMID 37273454, 2023). "To begin, we analyzed the COX7B expression profiles in several cancer types using data from TCGA's RNA sequencing project (including those cancers without normal tissues for comparison)." (PMID 37273454, 2023). "While Cox7b is not adapted as a direct target for the therapeutic prevention of brain metastasis, we believe that our general strategy, applied to other cancer types and/or different secondary sites, has the potential to unravel other, unprecedented target candidates." (PMID 36139533, 2022).
tumor (6 papers, 2018 to 2023). "Examination of the pathological features of these genes demonstrated that low COX7B levels were significantly associated with high tumor grade and advanced stage." (PMID 30367559, 2018). "The relationship between COX7B expression and tumor-infiltrating immune cells in ESCA was analyzed by using ssGSEA." (PMID 37273454, 2023). "This study underlined the clinical value of COX7B in ESCA and analyzed the effect of COX7B on immune infiltration in the tumor microenvironment." (PMID 37273454, 2023). "Individuals who have a low expression of COX7B and are undergoing tumor immunotherapy for ESCA may benefit more from this medication than other patients." (PMID 37273454, 2023). "Interestingly, high Cox7b expression was enhanced through rounds of in vivo selection using intracardiac delivery in mice, thus bypassing adaptation and selection in a primary tumor." (PMID 36139533, 2022). "Importantly, multivariate analysis for predicting the overall mortality discovered that a low COX7B level (P = 0.029) was a risk factor independent of patient age, tumor stage, and lymph node status." (PMID 30367559, 2018). "Tumor samples from patients, who underwent CDDP therapy, showed decreased COX7B protein levels after the treatment." (PMID 30367559, 2018).
neurodegenerative disease (2 papers, 2019 to 2026). A disorder of the central nervous system characterized by gradual and progressive loss of neural tissue and neurologic function. "Expression changes of COX7B have also been described during the development of neurodegenerative diseases." (PMID 30876387, 2019).
cardiovascular disease (1 paper, 2020). "In this pathway, upregulation of COX7B, COX17, and ATP6V1G3 as well as downregulation of COX6A2 and UQCRQ may lead to CKD complications with cardiovascular disease." (PMID 33247215, 2020).
infection (1 paper, 2024). The state of being infected such as from the introduction of a foreign agent such as serum, vaccine, antigenic substance or organism. "In male mice, there were 478 DEGs in the infection group (MT) compared with the control group (MC); 122 genes with upregulated expression, such as Ifitm1, Wfdc21, Wfdc17, and Adam8 (P < 0.001); and 356 genes with downregulated expression, such as Tuba1b and Cox7b (P < 0.001)." (PMID 40303139, 2024).
mitochondrial disease (1 paper, 2024). "Although not directly related to early ocular GRNs, mitochondrial disease caused by variants in HCCS, COX7B, and NDUFB11 has also been previously associated with MAC cases." (PMID 38821055, 2024).
COX7B also shares sentences with these, for which no sentence is quoted: Alzheimer disease (2 papers); COVID-19 (2); lung carcinoma (2); acute intermittent porphyria (1); adrenocortical carcinoma (1); ankylosing spondylitis (1); Anophthalmia (1); central nervous system disorder (1); cervical cancer (1); cervical squamous cell carcinoma (1); colorectal adenocarcinoma (1); endocervical adenocarcinoma (1); glioblastoma (1); Hepatic fibrosis (1); hypothyroidism (1); neuropathy (1); ovarian carcinoma (1); psoriatic arthritis (1); renal clear cell carcinoma (1); thyroid cancer (1).